LEPR (leptin receptor)
Diseases named in the same sentence as LEPR in open-access papers (continued):
Sharing a sentence is not in itself a finding about the gene and the disease.
breast cancer (continued). "Notably, our IHC staining of human specimens suggest that the proportions of cells with positive staining for the leptin receptor ObR, the macrophage marker CD68, and IL-8 increase as breast cancer progresses from carcinoma in situ to invasive carcinoma." (PMID 27588409, 2016). "As clinical implications, these data suggest that targeting leptin/leptin receptor signaling generated in the microenvironment may be useful for BCSC eradication and eventually to prevent recurrence and metastasis in patients with breast carcinoma." (PMID 26556856, 2016). "The relevance of leptin signalling in breast tumorigenesis is reinforced by the observation that both leptin and leptin receptor appear to be significantly overexpressed in breast cancer tissue relative to non-cancer epithelium." (PMID 19223908, 2009). "When we stratified the patients according to the menopause status (190 pre-menopausal and 118 post-menopausal) no significant changes in the LEP and LEPR genotype distributions were seen in breast carcinoma subgroups (data not shown)." (PMID 16504019, 2006). "However, it remains unclear from these studies whether the observed reduction in tumor growth with LEPR inhibition is due solely to effects on angiogenesis, as LEPRA2 also reduces Cyclin D expression in breast cancer cells in vitro." (PMID 39439572, 2024). "The correlation of expression of leptin receptor (OBR), leptin-targeted genes (CDK8, NANOG, and RBP-Jk), and breast cancer (BC) patient survival was determined from The Cancer Genome Atlas (TCGA) mRNA data." (PMID 32471192, 2020). "Interestingly, blocking leptin signaling by using a full leptin receptor antagonist, the peptide LDFI, completely reversed the breast CSC phenotype, further highlighting the potential advantage of targeting leptin signaling to block breast cancer malignancy." (PMID 30634494, 2019). "Therefore, the coexpression of HER2 and the leptin/LEPR system could contribute to increase the activity of HER2, reducing the sensitivity to monoclonal trastuzumab treatments for this type of breast cancer." (PMID 31380268, 2019). "Leptin and LEPR are overexpressed in breast cancer as compared to non-cancer mammary epithelium." (PMID 31380268, 2019). "Furthermore, some data indicate that weight gain is associated with poor outcomes in BC patients making it unclear whether potential benefits of LEPR inhibition of breast cancer angiogenesis would outweigh the negative effects of associated weight gain." (PMID 39439572, 2024). "However, leptin did not upregulate leptin receptor expression in breast cancer cells." (PMID 32836215, 2020). "Several peptide antagonists of LEPR (allo-aca, PEG-LPrA2 and LDFI) have been shown independently to be effective against both estrogen receptor positive (MCF7) or negative (MDA-MB-231) breast cancer xenograft models." (PMID 28542577, 2017).
metabolic syndrome (74 papers, 2011 to 2025). A cluster of metabolic risk factors for CARDIOVASCULAR DISEASES and TYPE 2 DIABETES MELLITUS. "The model we used was the pound mouse, which has a mutation in the leptin receptor, leading to hyperphagia and all of the features of the metabolic syndrome." (PMID 37238651, 2023). "Conversely, dyslipidemia was associated with a 2.1-fold (p = 0.014) decrease in LEPR mRNA in EAT and 2.3-fold decrease in IL6 in PVAT (p = 0.023)." (PMID 36157437, 2022). "The greater risk of developing metabolic syndrome conferred by the GG genotype of the leptin receptor genetic variant (rs3790433) was shown to be abrogated among individuals with a high intake of polyunsaturated fatty acids." (PMID 36432482, 2022). "Exposure to early adversity is associated with eating behaviour disorders and metabolic syndrome, but the role of the leptin receptor on this relationship is poorly explored." (PMID 36241774, 2022). "Third, genetic polymorphisms of 5-HT2C, leptin and leptin receptor have been proven to influence weight gain and metabolic syndrome during clozapine treatment; however, these pharmacogenetic parameters were not investigated in this study." (PMID 33277605, 2020). "In this study, we investigated the mechanism and effect of CPAE on obesity using leptin receptor-deficient SHR.Cg-Leprcp/NDmcr (SHR/cp) rats as a model of morbid obesity with metabolic syndrome (MetS)." (PMID 28684967, 2017). "Zucker rats possess a mutation in the leptin receptor and develop metabolic syndrome symptoms, including insulin resistance and dyslipidemia, at 4–5 weeks of age." (PMID 25007331, 2014). "Here, we report that mice globally deficient in the leptin receptor, which exhibit many features of the metabolic syndrome, had impaired viral clearance and reduced survival following influenza A infection." (PMID 25232724, 2014). "Metabolic syndrome model in Zucker fa/fa rats develops because of a mutation in the leptin receptor, which results in a deficiency in its signaling." (PMID 25324698, 2014). "The leptin receptor deficient spontaneously hypertensive rat (SHR-cp) is a well-established model of metabolic syndrome with hypertension, dyslipidemia, insulin resistance, and obesity." (PMID 23586038, 2013). "Whether LEPR polymorphisms are also associated with metabolic syndrome in BD patients receiving VPA remains to be further investigated." (PMID 36077028, 2022). "In summary, our findings suggest that LEP rs7799039 and LEPR rs1137101 are associated with the risk of MetS development and metabolic syndrome–related disorders in the Turkish population." (PMID 39136228, 2025). "We recently established a new animal model of metabolic syndrome (MetS), the DahlS.Z-Leprfa/Leprfa (DS/obese) rat, by crossing Dahl salt-sensitive (DS) rats with Zucker rats harboring a missense mutation in the leptin receptor gene (Leprfa)." (PMID 25111735, 2014). "In this study, we examined the prevention effects and mechanisms of large yellow tea water extract (LWE) on metabolic syndrome using leptin receptor knockout (Lepr−/−) rats." (PMID 35681388, 2022). "In the Women’s Genome Health Study, metabolic-syndrome related genes, such as LEPR, HNF1A, IL6R, and GCKR, were correlated to CRP expression and inflammation." (PMID 35845045, 2022). "Meanwhile, dyslipidemia associated with decreased ADIPOQ expression in EAT and PVAT, LEPR in EAT, and IL6 in PVAT." (PMID 36157437, 2022). "The selection of rats with a leptin receptor mutation is significant, since Zucker (Crl:ZUC(ORL)-Leprfa) strain is considered to represent metabolic syndrome, the weight loss itself seems to be a much bigger challenge than in primarily non-obese organisms." (PMID 33833309, 2021).
metabolic syndrome (continued). "The results showed that metabolic syndrome was correlated with higher levels of clozapine and CYP2C19*2 and leptin receptor G alleles." (PMID 33187329, 2020). "Thus, our work corroborated prior evidence that LEPR is associated with IR, which is a crucial feature of metabolic syndrome (MetS)." (PMID 32517169, 2020). "Leptin increased, whereas soluble leptin receptor and adiponectin decreased with increasing BMI and metabolic syndrome characteristics." (PMID 31453973, 2019). "Leptin receptor-deficient SHR.Cg-Leprcp/NDmcr (SHR/cp) rats spontaneously develop moderately elevated blood glucose with hyperphagia, insulin resistance, obesity, dyslipidemia and hypertension, traits that resemble those of human pre-diabetes and MetS." (PMID 25874615, 2015). "Similarly, EAT LEPR expression was lower in individuals with dyslipidemia, as was PVAT IL6 expression." (PMID 36157437, 2022). "Still, at least to our knowledge, no polymorphisms in the gene encoding LEPR has been linked to psoriasis so far, while in the case of the gene encoding leptin, rs7799039 was associated with the plasma leptin levels and the metabolic syndrome with psoriasis." (PMID 34685457, 2021). "Here, we found a slightly higher rate of dyslipidemia in LEPR wt/- than in wt/wt subjects." (PMID 34448070, 2021). "Little is known regarding the associations between high-molecular-weight (HMW-) adiponectin, leptin and soluble leptin receptor (sOB-R) and metabolic syndrome (MetS) in Chinese." (PMID 21347230, 2011). "A very recent two-hit approach combined metabolic syndrome, as a consequence of obese ZSF1 with double–leptin receptor defect, and pulmonary endothelial impairment by the VEGF receptor antagonist, SU5416." (PMID 38259266, 2023). "For the purpose of this study, we utilized the well-established leptin receptor knock-out model, mimicking human T2DM conditions including features of the metabolic syndrome." (PMID 25742620, 2015).
Hyperinsulinemia (43 papers, 2008 to 2025). An increased concentration of insulin in the blood. "In rodents and humans, LEP and LEPR deficiencies are associated with hyperinsulinemia, hypothyroidism, and hypogonadotropic hypogonadism resulting in delay or absence of pubertal development." (PMID 37659411, 2023). "Hyperinsulinemia, though significantly more pronounced in individuals with LEPR or MC4R deficiency compared with those with LEP deficiency, increased with age in all three mutant groups." (PMID 37659411, 2023). "This patient was also carrier of the LEPR rs3790433 GG genotype which is associated with reduced risk for hyperinsulinemia and IR upon adherence to high-n-3/low-n-6 polyunsaturated fatty acid (PUFA) diet." (PMID 35265654, 2022). "db/db mice spontaneously develop hyperinsulinemia due to mutation in the leptin receptor, which leads to impaired function of beta cells of the pancreatic islets." (PMID 29670682, 2018). "Leptin deficiency in ob/ob mice and leptin receptor deficiency in db/db mice led to hyperinsulinemia even before the progression of obesity and diabetes and this hyperinsulinemia was ameliorated by administration of recombinant leptin to the ob/ob mice." (PMID 24032047, 2013). "When LepR is unilaterally reactivated in the arcuate nucleus of the hypothalamus of mice that are otherwise LepR-deficient, body weight and adiposity are only slightly affected, but blood glucose and hyperinsulinemia are significantly improved." (PMID 40283443, 2025). "At the age of 10–15 years, hyperinsulinemia appeared milder in the group with LEP deficiency as compared with the patients with LEPR and MC4R deficiencies (mean 49 versus 104 and 66 μIU/mL in children with LEP, LEPR, or MC4R deficiency, respectively) (range of insulin assay: 0–300 μIU/mL)." (PMID 37659411, 2023). "For example, hypothalamus and pancreas-specific LEPR signaling disruption led to fasting hypoglycemia, hyperinsulinemia, and hypertriglyceridemia, highlighting the important role of beta cells in LEPR mediated glucose homeostasis." (PMID 20624279, 2010).
Hepatic steatosis (34 papers, 2013 to 2025). Steatosis is a term used to denote lipid accumulation within hepatocytes. "The deletion of the miR379 cluster attenuates hepatic steatosis and metabolic dysfunction of leptin-receptor-deficient type 2 mice induced by a high-fat diet, and the insulin-like growth factor 1 receptor is directly targeted by miR379." (PMID 38282657, 2024). "In the present study, we found that miR-30c-5p was significantly decreased in liver of leptin receptor deficient (db/db) mice, a classic animal model for liver steatosis." (PMID 28088781, 2017). "Additionally, adenovirus-mediated induction of MAPK kinase 1, the upstream regulator of ERK, notoriously relieved liver steatosis in leptin receptor-deficient mice." (PMID 34361079, 2021). "Likewise, NGF was elevated in leptin-receptor-deficient db/db mice, used as another model for fatty liver disease." (PMID 31296846, 2019). "Thus, the ChrSd-associated upregulation of hepatic leptin receptor expression and downregulation of plasma leptin concentration suggest that improved hepatic leptin sensitivity could, in part, contribute to reduced hepatic steatosis." (PMID 27977712, 2016). "Treatment of fructose-induced hepatic steatosis mice with 150 mg kg−1 body weight of kefir peptides significantly inhibited the expression of the leptin receptor (OB-R) and increased the expression of p-JAK2, STAT3 and p-STAT3." (PMID 27941940, 2016). "In leptin receptor-db/db mice, overexpression of Hrd1 has been shown to ameliorate liver steatosis." (PMID 39910053, 2025). "reuteri GL-104 decreased fasting blood glucose and lipid profiles, and improved glucose tolerance in genetic diabetic-obese (db/db) mice with a mutation in the leptin receptor Additionally, L. reuteri GMNL-263 improved insulin responses and ameliorated hepatic steatosis in high fructose-fed rats." (PMID 39520540, 2025). "First, the hepatic steatosis in SHROB rats only partially mimics the hepatic consequences of human MetS in light of the dissimilarities in the biology of leptin in rodents and man, where unequivocal involvement of leptin receptor in hepatic steatosis has yet to be demonstrated." (PMID 30201044, 2018). "Moreover, in the leptin/leptin receptor mice models, hepatic steatosis was more severe in ob/ob mice than in db/db mice – consist with a somewhat milder phenotype when deleting the receptor versus its ligand." (PMID 23341960, 2013). "Although pathological manifestation caused by the absence of a functional leptin receptor has been extensively studied in SHROB rats, it is unknown whether these animals elicited sex-specific differences in the development of hepatic steatosis." (PMID 30201044, 2018).
Hypertension (29 papers, 2009 to 2025). The presence of chronic increased pressure in the systemic arterial system. "Zohreh Nowzari20 searched for associations between LEP and LEPR gene polymorphisms and CADsusceptibility and hypertension among Iranians." (PMID 32049202, 2020). "The aim of the study was to study the association of the LEPR Gln223Arg with prevalence of hypertension in an urban Brazilian population." (PMID 24772364, 2014). "An SNP in ADIPOQ, rs266729, and another SNP in LEPR, rs12037879, were significantly associated with hypertension." (PMID 24414038, 2014). "For example, inherited risk alleles for high blood pressure in the LEPR gene affect the onset of hypertension predominantly in individuals with unhealthy life-style." (PMID 19562039, 2009). "It was also found that despite the lack of subcutaneous adipose tissue, and subsequently a lack of leptin, in individuals with lipodystrophy, congenital leptin deficiency, or biallelic leptin receptor gene variants some of those individuals still have hypertension." (PMID 37872379, 2024). "Indeed, carotid bodies denervation inhibits BP increase induced by leptin infusion in lean and obese mice whereas the expression of leptin receptor in the carotid bodies leads to hypertension in leptin receptor–deficient db/db mice." (PMID 38186879, 2024). "Thus, this study failed to provide evidence for a differential prevalence of mild hypertension by groups of the LEPR Q223R gene polymorphism." (PMID 24772364, 2014). "Arterial hypertension (AH) associated with low EAT and PVAT ADIPOQ, and high EAT LEP, SAT, as well as PVAT LEPR, and IL6 in SAT and EAT." (PMID 36157437, 2022). "It was also found that the selective overexpression of the leptin receptor in the carotid body in mice deficient of the leptin receptor enhanced TRPM7 gene expression and induced hypertension." (PMID 33679451, 2021). "In the present study, we found one intron SNP, rs13306519, in LEPR to be significantly associated with T2DM and another intron SNP rs12037879 was found to be significantly associated with hypertension." (PMID 24414038, 2014). "The purpose of the present study was to evaluate the association between four insulin resistance genes (ADIPOQ, LEPR, RETN, and TRIB3) and both T2DM and hypertension." (PMID 24414038, 2014). "In summary, the present findings suggest that variants in ADIPOQ and LEPR are significant risk factors for T2DM and hypertension." (PMID 24414038, 2014). "Another intron SNP (rs12037879) in LEPR and a promoter region SNP (rs266729) in ADIPOQ were significantly associated with hypertension (P = 0.041 and 0.042 respectively)." (PMID 24414038, 2014). "In the LEPR gene the haplotype TATCA (rs1887285, rs17097182, rs10889553, rs970467, rs9436746) was associated with hypertension (P = 1.7×10−4, OR = 2.19; hypertensives 8%; normotensives 4%) and higher SBP (P = 2.8×10−4, Mann-Whitney test)." (PMID 19562039, 2009). "We identified haplotypes of LEPR, but also PTGER3 gene, which were associated with increased risk for hypertension in KORA S3 study population." (PMID 19562039, 2009). "In total, 12 markers in 7 genes (ADRA2A, LEP, LEPR, PTGER3, SLC2A1, SLC4A2, SLC8A1) revealed considerable association (P<10−3) either with SBP, DBP, and/or hypertension (HYP)." (PMID 19562039, 2009). "Although Allo-aca penetrates the BBB, the dichotomy between the absence of central metabolic and respiratory effects of this leptin receptor blocker and the presence of hypotensive effects suggest that leptin may act peripherally to induce hypertension." (PMID 34276408, 2021). "Furthermore, overexpression of the leptin receptor selectively in the carotid body of leptin receptor-deficient mice enhanced TRPM7 gene expression and induced hypertension." (PMID 32982794, 2020). "In conclusion, this study does not provide evidence for a role of the LEPR gene Gln223Arg polymorphism in increasing the prevalence of mild hypertension in a cross-sectional population-based study." (PMID 24772364, 2014).
Hypertension (continued). "We found several SNPs in LEPR and ADIPOQ to be significantly associated with T2DM and hypertension." (PMID 24414038, 2014). "The aim of the study was to investigate whether the Gln223Arg in the leptin receptor (LEPR) influences the prevalence of hypertension." (PMID 24772364, 2014). "In order to explore the potential association between the leptin receptor (LEPR) gene polymorphisms and essential hypertension (EH) risk in the Northern Han Chinese population, we recruited 823 hypertensive subjects and 491 healthy control subjects from the Northern Han Chinese." (PMID 24522342, 2014). "Furthermore, to clarify which hypertension-related stress activates leptin and leptin receptor expression, we measured leptin and leptin receptor mRNA expression in isolated ventricular myocytes stimulated with angiotensin-II (ANGII), endothelin-1 (ET-1), or mechanical stretch." (PMID 23270329, 2012). "SNP–SNP interaction analysis identified a significant interaction between two SNPs rs13306519 in LEPR and rs266729 in ADIPOQ for T2DM (P_int = 0.012, OR_int = 2.67) and hypertension (P_int = 0.0041, OR_int = 2.23)." (PMID 24414038, 2014). "A significant interaction was observed between two SNPs rs13306519 in LEPR and rs266729 in ADIPOQ for T2DM (P_int = 0.012, OR_int = 2.67) and hypertension (P_int = 0.0041, OR_int = 2.23)." (PMID 24414038, 2014). "The strongest associations were detected between rs10954174 in Leptin (LEP) gene and DBP (P = 5.2×10−5, linear regression); between rs10889553 in Leptin receptor gene (LEPR) and SBP (P = 4.5×10−5, linear regression) as well as hypertension (P = 4.14×10−4, logistic regression)." (PMID 19562039, 2009). "We hypothesize that systemic leptin receptor blocker Allo-aca will treat hypertension in NZO mice without any effect on body weight, food intake, or breathing." (PMID 34276408, 2021).